LAMP1 (lysosome associated membrane protein 1)
Diseases named in the same sentence as LAMP1 in open-access papers (continued):
Sharing a sentence is not in itself a finding about the gene and the disease.
infection (continued). "Although we observed enrichment of lysosomal proteins in the media, we did not detect LAMP-1 on the cell surface during infection, suggesting this was not reflective of lysosomal exocytosis." (PMID 40274809, 2025). "At 4 h post-infection, the ΔgntR8 mutant displayed a significantly higher LAMP-1 colocalization rates rather than the wild-type (WT) (p = 0.003), indicating impaired lysosomal evasion." (PMID 41235247, 2025). "We measured the expression of LAMP-1 (human), a transmembrane glycoprotein that can be found in lysosomes, ATPase, and TSPAN8 transmembrane protein in CRFK-derived EVs’ post-infection." (PMID 39091390, 2024). "Next, we investigated whether the inhibitory effect of U-73122 on LCMV infection extended to the infection mediated by the LASV glycoprotein that used a different cell entry factor, LAMP1." (PMID 39688895, 2024). "Surprisingly, bacteria and LAMP1 do not colocalize in either 1° or 2° infections, suggesting that lysosomes are not filled with bacterial products." (PMID 38956024, 2024). "For example, neither genotype, infection mode, nor post-infection time significantly altered the levels of LAMP1 mRNA." (PMID 38051049, 2024). "No co-localisation of LAMP1 was observed with either NVL or RPL5 at 48 h post-infection nor with 4HA or 3FLAG-tagged NyxA, suggesting the absence of autophagosome formation." (PMID 36609656, 2023). "Three doses of LAMP1-CCHFV-NP vaccination in mice resulted in a balanced Th1 and Th2 response, specific anti-NP antibodies, and CTL responses as well as the strongest protection against CCHFV tecVLP infection." (PMID 37753088, 2023). "The authors described that between 48 and 72 h postinfection, the BCV acquires LAMP-1, as well as autophagic features, and that this vacuole, which the authors named autophagic BCV (aBCV), contributes to the formation of infection foci that neighbor the infected cells." (PMID 36622142, 2023). "This LAMP-1 staining profile was identical to that observed in CAB2-GFP infections without CNF1 at 1 h PGT, when the endosomes surrounding bacteria are coated in LAMP-1." (PMID 35862776, 2022). "To delineate the role of LAMP1 in LASV entry, we developed assays to monitor the formation of nascent fusion pores, as well as their initial and complete dilation to sizes that allow productive infection of avian cells by LASV GPC pseudoviruses." (PMID 35969633, 2022). "The results of in vitro infection assays in which colocalization of intracellular parasites with LAMP-1-positive vacuoles was determined did not confirm previous observations suggesting a role for TS in parasite escape from PV." (PMID 35073735, 2022). "Recent studies by others and our group have shown that hLAMP1, while promoting LASV fusion and infection, is not absolutely required for virus entry, since cells lacking human LAMP1 support basal levels of LASV fusion/infection." (PMID 35969633, 2022). "In contrast to our findings with WT bacteria, the proportion of ΔalgR bacteria that colocalized with LAMP-1 did not increase throughout the time course of infection." (PMID 33901267, 2021). "Using stably LAMP1-GFP-transfected HeLa cells, we performed automated microscopy on a spinning disk confocal microscope (SDCM) system with time-lapse live cell imaging (LCI) of STM infection and scored for altered SIF formation as phenotypic readout." (PMID 32658937, 2020). "In that work we established that formation of the vacuole is extended up to 1 h after infection followed by vacuole maturation which was characterized by the arrival and fusion of VAMP7 and Lamp1-positive vesicles and vacuole acidification from 1 h to around 6 h after infection." (PMID 33194787, 2020). "We found that treatment with mito-TEMPO led to enhanced co-localization with LAMP-1 at 24 h but not 4 h after infection." (PMID 32210476, 2020).
infection (continued). "The confocal microscopy evidence indicated that M1 GAS strain SF370 infection changed the distribution of enhanced green fluorescent protein (EGFP)-LC3 from being diffuse to aggregating as puncta, and M1 GAS strain SF370, LC3, and LAMP1 were colocalized." (PMID 32518187, 2020). "Furthermore, JUNV infection induced the colocalisation of p62, ATG16, RAB5, RAB7A and LAMP1 with the autophagosomal LC3 protein." (PMID 31216340, 2019). "LCMV GPC-mediated infection, entry, and fusion were not affected by the absence of Lamp1, and loss of CD63 did not impair LCMV GPC-mediated infection." (PMID 29295909, 2018). "(i) A robust (~85%) decrease in Lamp1 expression does not dampen the efficiency of LASV pseudovirus infection of 293T cells over a range of input multiplicities." (PMID 29295909, 2018). "Since LCMV GPC does not interact with Lamp1, LCMV infections were, as expected, unaffected by decreased Lamp1 expression." (PMID 29295909, 2018). "In this manner Lamp1 increases the overall efficiency of LASV entry and infection." (PMID 29295909, 2018). "In marked contrast, infection of NHBE cells with transiently restricted NTHI results in a LAMP1 staining pattern that is almost entirely diffuse, suggesting that localization of LAMP1 is altered." (PMID 30209128, 2018). "Moreover, results from our KD analysis indicate that a low level of Lamp1 (~15% of WT) in 293T cells suffices for efficient LASV GPC-mediated entry and infection." (PMID 29295909, 2018). "LAMP1 recruitment to intraepithelial bacteria was observed following infection with wild type but not ΔsopABE2 or ΔsopABsipA Salmonella." (PMID 29522566, 2018). "A leading candidate, Lamp2, is not likely to play such a role: it did not emerge in the screen for pro-LASV factors, did not rescue infection in Lamp1 KO cells, and does not appear to physically interact with LASV GPC." (PMID 29295909, 2018). "After the FMDV-containing macropinosomes were dissociated from the plasma membrane, they were soon colocalized with EEA1-labeled early vesicles but did not colocalize with LAMP1-positive late vesicles during the whole infection period." (PMID 26757826, 2016). "There was no LAMP1 signal observed in initial period of time (at 15 min) in both types of infection." (PMID 27014637, 2016). "Nearly 90% of the translocon protein SseB was co-localized with LAMP-1 by 3.5 h and this level did not change up to 6 h post-infection." (PMID 25875623, 2015). "LAMP1, also known as CD107a, was recently identified in EVT where its expression correlated with the ability of EVT to resist infection from Listeria monocytogenes, suggesting that EVT may have a bactericidal phenotype." (PMID 22359590, 2012). "Thus, promastigote PVs delayed acquisition of LAMP-1 for at least 24 h after infection, whereas most amastigotes resided in PVs that acquired LAMP-1 quickly after infection." (PMID 21552562, 2011). "At time zero after infection, LAMP-1 and LAMP-2 showed little or no co-localisation with phagosomes." (PMID 21426584, 2011). "At 1 h post-infection, 80% of the promastigotes resided in LAMP-1-negative PVs whereas 20% were LAMP-1+." (PMID 21552562, 2011). "Taken together, we show here for the first time that the IFNγ-induced endogenous Irgm1 localises to the late endocytic/lysosomal (LAMP1-positive) compartments in addition to the Golgi apparatus in the absence of infection." (PMID 20072621, 2010). "Further, CLDC+MPF treatment did not inhibit the ability of SchuS4 to escape into the cytosol of infected cells as evident by the absence of SchuS4 co-localization with LAMP-1 4 hours after infection in all treatment groups." (PMID 20523903, 2010). "Confocal microscopy of infected intestine 407 cells, using an antibody against the late endosomal marker LAMP1, demonstrated that AIEC co-localized with this marker after 4 h of infection, indicating that vacuoles containing invasive AIEC were directed to the endosomal pathway in epithelial cells." (PMID 19709415, 2009).
infection (continued). "At 24 hours post-infection, Mm that polymerized actin were not ubiquitinated, whereas ubiquitinated Mm were found within LAMP-1–positive vacuoles resembling lysosomes." (PMID 19436699, 2009). "Bacteria introduced in the secondary infection were rarely found in macrophages, were mostly extracellular, and did not colocalize with LAMP-1, in agreement with a report for Salmonella Typhimurium that the frequency of macrophage reinfection after the primary infection is rare." (PMID 38722166, 2024). "Of particular interest, the expression of 6 genes (VSIG4, LAMP1, QPCT, C1QB, TNFSF13, and JUN) can be used to distinguish the transcriptomic signature of a dormant infection from an uninfected joint replacement highlighting the potential for these markers in diagnosing a dormant infection." (PMID 39563367, 2024). "In contrast, the lack of a strong effect on viral fusion and infection of DF-1 cells was unexpected, suggesting that endosomal factors other than LAMP1 may facilitate LASV fusion in DF-1 cells." (PMID 35969633, 2022). "When GFP-VLPs were used to infect mCherry-LAMP1 expressing target cells, GFP and mCherry signals colocalized with an average Pearson’s coefficient of 0.137, which was statistically significant when compared with GFP-VLP infection of mock transfected cells (0.021)." (PMID 33214224, 2021). "Indeed, the GFP-expressing bacteria co-localized with LAMP-1-positive compartments over the entire time period of observation (i.e. from 2 h to 144 h p.i.), both in the barrier and confluent infection models, and irrespective of the investigated strain." (PMID 33222653, 2020). "(ii) Knockout of Lamp1 expression in 293T cells diminishes, but does not abolish, entry and infection (shown using three different sets of LASV pseudoviruses bearing different reporters [luciferase, GFP, and βlaM] as well as different viral cores [VSV and MLV])." (PMID 29295909, 2018). "Interestingly, the late endosomal/lysosomal protein LAMP-1 was recruited to S. aureus phagosome but no tubular structures labeled with LAMP-1 were observed at 1–2 h post-infection." (PMID 29046869, 2017). "When cells were pretreated with CQ, which is an inhibitor that prevents autophagosome-lysosome fusion, PFV infection could not induce the co-localization of LAMP1 and LC3." (PMID 28270144, 2017). "However, HRV1B infection resulted in the concentration of cholesterol at the plasma membrane, with almost no colocalization with LAMP-1." (PMID 26976677, 2016). "Moreover, the simultaneous labeling of infected cells with LAMP1 antibody and Bodipy 493/503 in fixed cells at 24h post infection also shows that the presence of LD is not restricted to the LAMP1 stained parasitophorous vacuoles." (PMID 26871576, 2016). "The confocal microscopy data suggest that wbtA::Tn5, wzy::Tn5, manB::Tn5 and FTT0846::Tn5 strains were phagocytosed to the same extent as wild type, and did not colocalize with the Lamp-1 lysosomal marker, despite diminished intracellular growth at later stages of infection." (PMID 25999917, 2015). "At later time points after infection, the SCV acquires certain characteristics of late endosomal/lysosomal compartments such as (i) the presence of a subset of Rab GTPases, such as Rab7, (ii) lysosomal glycoproteins (lgp), such as LAMP1, (iii) acidification, and (iv) juxtanuclear positioning." (PMID 25254663, 2014). "We could not detect colocalization with the late lysosomal markers LAMP1 and cathepsin D, or with the early endosomal marker Rab5 after 24 h of infection." (PMID 23862148, 2013). "Phagosomes of MH-S cells containing pre-swollen conidia of either A. fumigatus or A. terreus successfully underwent fusion with lysosomes 3 h and 8 h (data not shown) after infection as indicated by the presence of LAMP-1 and Cathepsin D, characterizing a mature phagolysosome." (PMID 22319619, 2012).
infection (continued). "Twenty-four hours after infection, no parasites could be co-stained with anti-LAMP-1 whether they were in the cytoplasm of CK18 RNAi-treated or non-treated cells." (PMID 19087356, 2008). "At different times post-infection, the frequency of parasites co-stained with the phagolysosomal marker LAMP-1 was similar among infected HeLa cells, regardless of whether they were transfected with CK18 RNAi." (PMID 19087356, 2008). "Similarly, there was no change in the host LAMP1 levels after infection in the PEX5 KO cells." (PMID 39695325, 2025). "Moreover, vesicles positive for LAMP1, a lysosomal marker protein, proposed to be used as a nutrient source by the parasite for its fast development inside hepatocytes, surround Plasmodium throughout infection without fusing with the PVM14." (PMID 33214643, 2020). "LAMP1-CCHFV-Gn-vaccinated mice exhibited only specific anti-Gn antibodies and did not offer sufficient defense against CCHFV tecVLPs infection." (PMID 37753088, 2023). "In these cells, pSTING and pTBK1 lingered 8 h after infection, and endogenous STING accumulated at Lamp1-negative perinuclear compartments." (PMID 36918692, 2023). "In response to infection with H37Rv (L4), as a reference strain, the expression of ATG 16L1, ATG7, and LAMP1 genes decreased (p < 0.05), while no changes were observed in the expression of other genes." (PMID 36000264, 2022). "It has been proposed that LAMP1 increases efficiency of LASV entry and infection by elevating the pH threshold for GPC-mediated fusion, thus avoiding virion inactivation by low pH and proteases, which are usually present in LAMP1-negative endosomes." (PMID 34747339, 2021). "In control experiments, LAMP1 knock down did not influence infection of HEK293T cells by particles pseudotyped with Influenza A virus hemagglutinin (IAVpp), but enhanced IAVpp infection of A549 cells." (PMID 34492091, 2021). "In line with previous reports, infection with rVSV-LASVGP, but not rVSV-LCMVGP, critically depended on LAMP-1." (PMID 30914516, 2019). "Our results showing that JUNV infection induces the colocalisation of RAB5, RAB7A or LAMP1 and LC3, indicate that phagophore or autophagosome fusion with early and late endosomes is not being blocked by JUNV infection." (PMID 31216340, 2019). "The fusion-enhancing effect of Lamp1 is also specific, as it is not seen for LCMV GPC-mediated entry or infection." (PMID 29295909, 2018). "When the samples were categorised based on the presence of intervillositis regardless of infection status, placentas with intervillositis showed higher densities of both LC3B (P = .01) and LAMP1 (P = .01) puncta compared to placentas without intervillositis." (PMID 29125872, 2017). "When the samples were categorised based on the presence of intervillositis regardless of infection status, placentas with intervillositis showed higher LC3B/LAMP1 colocalized volume compared to placentas without intervillositis (P = .0001)." (PMID 29125872, 2017). "In contrast, most RFP puncta colocalized with LAMP1 and were negative for GFP at 48 hours post-infection." (PMID 25807108, 2015). "The lack of co-localization between HIV-1 and LAMP-1 in mDC-LPS and mDC-IFNα indicates that HIV-1 did not traffic to the lysosome for degradation in either cell type at 2 h post-infection." (PMID 21504576, 2011). "As opposed to LAMP1-CCHFV-NP, mice immunized with LAMP1-CCHFV-Gc exhibited mostly specific anti-Gc and neutralizing antibodies as well as some protection against CCHFV tecVLPs infection." (PMID 37753088, 2023). "Unexpectedly, ectopic expression of hLAMP1 has a relatively modest effect on LASV fusion/infection with endosomes across three platforms–LASVpp, LASV-VLP and recombinant LCMV/LASV-GPC viruses, even in avian cells expressing a LAMP1 ortholog that does not support LASV fusion." (PMID 35969633, 2022). "The absence of Lamp1 reduces, but does not eliminate, LASV GPC-mediated entry and infection." (PMID 29295909, 2018).
infection (continued). "When the subcellular localization of live cpsII parasites was examined, it was apparent that these parasites did not colocalize with either Irgb6 or LAMP-1 in IFN-γ-activated or untreated macrophages, at any time point examined (ranging from 3 hours post-infection to 5 days post-infection)." (PMID 24722202, 2014). "Despite any potential issues with marker specificity, neither our lysosomal markers (LysoTracker, Lamp-1, and Lamp-2), nor our trans-Golgi marker, WGA, indicated co-localization with anti-V Ab after 30–45 min of infection as was observed with our M6P and rab7 Abs." (PMID 19609450, 2009). "However, we also noticed that a portion of Rab32-positive phagosomes are free of late endosomal markers (LAMP1 and LAMP2) and late endosomal/lysosomal probe (Lysotracker) from 1 to 6 h after infection, suggesting that not all Rab32-positive phagosomes are fused with late endosomes." (PMID 31199852, 2019). "Consistent with this, we recently showed that later in infection, RCV displaying VapA at the membrane and containing replicating R. equi were lacking lysosomal membrane protein 1 (LAMP-1), whereas RCV without VapA at the membrane were LAMP-1 positive and contained fewer bacteria." (PMID 30286098, 2018).